BCL2 (BCL2 apoptosis regulator)
Diseases named in the same sentence as BCL2 in open-access papers (continued):
Sharing a sentence is not in itself a finding about the gene and the disease.
uveal melanoma (10 papers, 2012 to 2025). A melanoma derived from melanocytes of the uveal tract. "Previous studies showed that inhibition of BCL-2 alone by antisense oligonucleotides caused cell death of uveal melanoma cells and that reduction in BCL-2 through the use of miR-182 suppressed the in vitro and in vivo growth of uveal melanoma cells." (PMID 32337074, 2020). "The effects of HAX-1 on mitochondrial-dependent induction of uveal melanoma cell apoptosis are caused by activating the PI3K/AKT/eNOS signal path and favorable modulation of Bax, caspase 3, and Bcl2." (PMID 35602302, 2022). "Zeaxanthin, a carotenoid pigment, has also been shown to decrease uveal melanoma cell viability through BCL-2 inhibition." (PMID 32337074, 2020). "Bcl-2 is another member of the intrinsic apoptotic pathway and has been reported to be highly expressed in uveal melanoma." (PMID 28863158, 2017). "Using four well-characterized uveal melanoma PDXs, we have shown that a specific Bcl-2/Bcl-XL inhibitor only had a moderate efficacy when administered alone, except in one model (MP41) with a clear dose-dependent in vivo efficacy." (PMID 24454684, 2014). "Taking together, our results clearly demonstrate that Bcl-2/Bcl-XL targeting is a promising therapeutic approach for uveal melanoma." (PMID 24454684, 2014). "To examine other intracellular proteins affected by miR-182 in uveal melanoma cells, we next determined the expression patterns of intracellular proteins directly affected by miR-182, including BCL2, cyclin D2, and other cell cycle related proteins." (PMID 22848417, 2012). "Corresponding to the constitutive activation of NF-κB, untreated uveal melanoma cells expressed moderate basal level of anti-apoptotic protein Bcl-2, while BAY11-7082 treatment remarkably reduced its expression." (PMID 23443086, 2012). "Corresponding to the basal and constitutive NF-κB activity, we found that untreated uveal melanoma cells constitutively expressed a moderate level of Bcl-2, while treatment with BAY11-7082 reduced its expression." (PMID 23443086, 2012). "Therefore, inhibition of anti-apoptotic BCL-2 proteins by ABT-263 alone or in combination with an ER stress inhibitor represents a potential therapeutic strategy in uveal melanoma treatment." (PMID 32337074, 2020). "BCL-2 was also previously shown to be overexpressed in uveal melanoma compared to normal tissue." (PMID 32337074, 2020). "In contrast to the high number of reports in various hematologic and solid tumors including cutaneous melanoma, only one in vitro study has evaluated Bcl-2 targeting in uveal melanoma cells, showing synergistic effect with chemotherapy and multi-drug resistance reversion." (PMID 24454684, 2014). "Indeed, human uveal melanomas are characterized by a high average percentage of Bcl-2 positive cells of 82% (range: 44%–100%), but without any prognostic impact." (PMID 24454684, 2014). "Altogether Bax expression was not altered, the down-regulation of Bcl-2 expression and the decreased ratio of Bcl-2/Bax might be mechanistically responsible for the reduced uveal melanoma cell survival following BAY11-7082 treatment." (PMID 23443086, 2012). "Nonetheless, the inhibition of anti-apoptotic Bcl-2 by BAY11-7082 may contribute to its effects to induce apoptosis of uveal melanoma cells." (PMID 23443086, 2012). "In this study, we systematically evaluated gene function in laboratory models of uveal melanoma, identifying critical contributions from signaling pathways including JAK/STAT, BCL2/BCL-XL, PI3K/mTOR, and Hippo." (PMID 41514587, 2025). "In contrast, we showed that ABT-263 which targets BCL-2 and BCL-xL has anti-proliferative and pro-apoptotic activities in uveal melanoma cell lines." (PMID 32337074, 2020).
uveal melanoma (continued). "Altogether, inhibition of anti-apoptotic BCL-2 proteins by ABT-263 induces a protective feedback response in 92.1 and Mel270 uveal melanoma cells, via induction of the ER stress response that can be prevented with PERK inhibitor." (PMID 32337074, 2020). "Yan and coworkers found similar effects in uveal melanoma cells, where they identified MITF, BCL2 and cyclin D2 as potential targets of miR-182." (PMID 24575749, 2014). "Finally, this research demonstrates for the first time that HAX-1 triggers uveal melanoma cell apoptosis via mitochondria dependence via the stimulation of PI3K/AKT/eNOS signal path and favorable modulation of Bax, Caspase 3, and Bcl2." (PMID 35602302, 2022). "Although Bcl-2, an anti-apoptotic protein known to be upregulated in uveal melanoma, was decreased in 5 of 7 samples, no clear pattern was seen with markers of proliferation or metabolic activity to further explain the lack of tumor response with treatment." (PMID 34771668, 2021). "Consistent with this notion, our results showed that ABT-199 (mainly directed against BCL-2) lacked efficiency in killing uveal melanoma cells." (PMID 32337074, 2020). "In primary uveal melanoma, expression of BCL-2 is significantly higher compared to normal ocular structures, or choroidal melanocytes, suggesting that it may be involved in the development and progression of these lesions." (PMID 32337074, 2020). "Thus, Bcl-2 was decreased by BAY11-7082 treatment and could help to explain why NF-κB blockade induced apoptosis in uveal melanoma cells." (PMID 23443086, 2012). "However, Bcl-2 expression level was not well correlated with clinical or histologic prognostic parameters or survival in uveal melanoma." (PMID 23443086, 2012).
ameloblastoma (9 papers, 2013 to 2025). The most common odontogenic tumor, arising from the epithelial component of the embryonic tooth and usually affecting the molar-ramus region of the mandible or maxilla. "This study was performed to compare the immunoexpression of Survivin with Bcl-2, Bax, and Ki-67 and to associate them with the histopathological type of each variant of ameloblastoma." (PMID 25866434, 2015). "Lower expression of Bcl-2 was described in OKCs/S compared to conventional ameloblastoma (AMc) and unicystic ameloblastoma (UA)." (PMID 40818142, 2025). "Expression of Bcl-2 was higher in the peripheral layer of ameloblastomas and the basal layer of OKCs." (PMID 33374329, 2020). "In a previous study, we demonstrated that BCL-2, which prevents apoptosis, was mainly expressed in the outer layer of ameloblastoma cells, whereas the inner cells (stellate reticulum-like cells and squamoid cells) did not express this protein." (PMID 23835807, 2013). "Ameloblastomas showed stronger Bcl-2 expression than OKCs and radicular cysts." (PMID 33374329, 2020). "In conclusion, our data show that cytoplasmic expression of Survivin and the expression of Bcl-2 and Bax are relate with behavior of ameloblastomas and possibly the higher expression for Ki-67 and nuclear Survivin in UA are associate with the epithelial morphology." (PMID 25866434, 2015). "This expression pattern of BCL-2 was similar to that of SHH in ameloblastoma." (PMID 23835807, 2013). "The purpose of this experimental study was to compare the immunohistochemical expression of SOX2 and BCL-2 in Odontogenic Keratocyst (OKC) and Ameloblastoma (AB) specimens, and to identify a possible correlation in their expression." (PMID 31967981, 2020). "Key words:Odontogenic keratocyst; Ameloblastoma; Odontogenic tumor; SOX2; BCL-2." (PMID 31967981, 2020). "All cases of ameloblastoma and OKC, but no dentigerous cyst cases, were positively stained for Bcl-2." (PMID 33374329, 2020).
anaplastic large cell lymphoma (9 papers, 2014 to 2024). Anaplastic large cell lymphoma (ALCL) is a rare and aggressive peripheral T-cell non-Hodgkin lymphoma, belonging to the group of CD30-positive lymphoproliferative disorders, which affects lymph nodes and extranodal sites. "Lymph node biopsy showed intermediate to large atypical monomorphic lymphocyte cells with ALK, CD30, CD5, CD3, CD45, and BCL-2 (weak positive) positivity and Ki-67-95%, suggestive of anaplastic large cell lymphoma (ALCL)." (PMID 38650799, 2024). "Inhibition of mTOR with rapamycin- or mTOR-specific small interfering RNA downregulated Bcl-2 and Mcl-1 in anaplastic large-cell lymphoma cells." (PMID 24647338, 2014). "Moreover, rarer sub-entities such as MYC and BCL2 “double hit lymphomas” (DHL), IRF4-rearranged large cell lymphoma (IRF4-LCL), and Burkitt-like lymphomas with 11q aberration pattern (mnBLL-11q) attracted interest while their relatedness regarding the major classes is still unclear in many respects." (PMID 35884496, 2022). "Anaplastic large cell lymphoma (ALCL) and primary effusion lymphoma (PEL), 2/22 entities covered by this panel, stood out by high expression of MCL1 and low expression of BCL2." (PMID 35058488, 2022).
fibrosis (9 papers, 2012 to 2025). the formation of excess fibrous connective tissue in an organ or tissue in a reparative or reactive process. "Of the individuals tested in these Bcl-2 assays, 3 had fibrosis scores of F3-F4 and 6 had scores of F0-F2." (PMID 27315061, 2016). "In this article we provided evidence that transplantation of MSCs attenuated cardiac fibrosis associated with DOX, increased Bcl2 expression in the-myocardium treated with DOX and exerted anti-fibrotic and anti-apoptotic effects on the myocardium, probably by acting in a paracrine manner." (PMID 23508361, 2012). "Moreover, miR-1 overexpression also inhibited cardiac fibrosis and apoptosis by reducing the mRNA expression of transforming growth factor beta-1 (Tgfb1) and increasing protein expression of Bcl-2, while reducing the level of Bax, thereby altering the Bcl-2/Bax ratio." (PMID 38132140, 2023). "In addition to BCL2, all targets may be the core targets of TPL for the treatment of extraocular muscle fibrosis in GO." (PMID 41212870, 2025).
kidney (9 papers, 2013 to 2025). "Particularly,Bcl-2 over-expression was revealed to be afrequent molecular event involved in the firststage of bladder carcinogenesis." (PMID 24381861, 2014). "Consistent with the repression of STAT3 pathway, which are highly relevant to bladder carcinogenesis, the suppression of STAT3 was further confirmed by the reduction of its downstream targets, such as Bcl-2, Bcl-xL and Mcl-1, at both mRNA and protein levels." (PMID 25849286, 2015). "In conclusion, our results verify the reno-protective potential of AEA against HgCl2-induced kidney injury by its anti-inflammatory, antioxidant, and anti-apoptotic capacities by modulating WNT-5A/BCL-2, IP3/NFATC1, HMGB-1/RAGE/NF-κB, caspase-1/IL-18, and caspase-3/BCL-2 cues." (PMID 37488162, 2023).
pancreatic ductal adenocarcinoma (9 papers, 2016 to 2026). An infiltrating adenocarcinoma that arises from the epithelial cells of the pancreas. "Similarly, miR-181b was found to enhance the sensitivity to gemcitabine in pancreatic ductal adenocarcinoma cells in vitro by binding to BCL-2 mRNA 3’UTR." (PMID 36613487, 2022). "Treatments induced apoptosis, increased BAX/BCL-2 ratio and suppressed the expression of SOX9 and SOX18, genes shown to be significantly up-regulated in pancreatic ductal adenocarcinoma." (PMID 35408514, 2022).
papillary thyroid carcinoma (9 papers, 2010 to 2025). "Knockdown of SERPINE2 in human papillary thyroid cancer cells decreased the antiapoptotic protein Bcl-2 and increased the proapoptotic protein Bax and caspase-3, thereby promoting cell apoptosis." (PMID 36505099, 2022). "The tumour suppressing function of this miRNA was also characterized in thyroid papillary carcinoma via downregulation of Bcl-2." (PMID 33610185, 2021). "Meng has found that autophagy inhibitor in combination with VEGFR2 inhibitor Apatinib can further inhibit papillary thyroid carcinoma cell proliferation and induce PARP/Bcl-2-mediated apoptosis." (PMID 33860036, 2021).
plasma cell neoplasm (9 papers, 2018 to 2025). A clonal proliferation of immunoglobulin-secreting plasma cells. "BCL-2 inhibition, primarily with venetoclax, represents a promising therapeutic option for plasma cell neoplasms beyond MM." (PMID 40190562, 2025). "Furthermore, most of the DLBCL and plasma cell neoplasms developed by the TRAF3/BCL-2 double-tg mice are composed by expanded transformed clones that have also undergone class switching and SHM." (PMID 30687320, 2018). "All consisted of plasma cell tumors, whatever the genotype, and whether or not the tumor was preceded by overt polyclonal plasmacytosis as seen in the Igκ-BCL2 mice." (PMID 36358756, 2022). "Biopsy revealed a kappa-restricted plasma cell neoplasm with strong CD138, BCL2, CD20, and PAX5 expression and absence of MYD88 L265P mutation via immunohistochemistry." (PMID 41346800, 2025).
polycystic kidney (9 papers, 2004 to 2022). "This indicates that loss of Bcl-2 or loss of polycystin-1 elicit polycystic kidney disease through different mechanisms." (PMID 23076254, 2013). "Mice deficient in the anti-apoptotic Bcl-2 gene develop polycystic kidney disease characterized by dilated proximal and distal tubular segments and hyper-proliferation of the epithelium and interstitium." (PMID 23076254, 2013). "In fact, Bcl2 deficient mice develop polycystic kidneys characterized by dilated proximal and distal tubules." (PMID 15357873, 2004). "Moreover, studies of Bcl-2-deficient mice at one week of age show growth retardation and develop renal hypoplasia, polycystic kidneys, fulminant apoptosis of the thymus and spleen, and lymphocyte loss, demonstrating that alteration of the Bax/Bcl-2 ratio promotes cell death." (PMID 36500363, 2022). "All Bcl-2−/− mice that we produced had short ears, soon became runts, and succumbed to polycystic kidney disease between the third and eighth week of life." (PMID 26452131, 2015). "Deletion of the anti-apoptosis gene, Bcl-2, resulted in polycystic kidney formation (similar to PKD), demonstrating that controlled tubular cell death may play an active role in physiological renal tubular formation." (PMID 29889867, 2018). "While ablation of the pro-apoptotic Bim prevented the development of polycystic kidney disease in mice deficient in Bcl-2, this was not the case in polycystin-1-deficient mice." (PMID 23076254, 2013).
steatosis (9 papers, 2014 to 2026). Increased lipid within the cytoplasm of cells. "Treatment with Que-CH significantly reduced serum IL-1β, improved liver histology by decreasing macro- and microvesicular steatosis, and lowered the Bax/Bcl-2 ratio, indicating reduced hepatocyte apoptosis." (PMID 41971603, 2026). "Conversely, liver sections of the DEXA group showed diffuse strong cytoplasmic expression of caspase-3 in the hepatocytes with macrovesicular steatosis and minimal faint expression of BCL2." (PMID 39736705, 2024). "In the present study, CO (5 g/kg) was able to reverse the degree of steatosis, improve the ultrastructure, increase Bcl-2 levels, and decrease the Bax and Bax/Bcl-2 ratios in the animals in the HF group." (PMID 38831961, 2024). "This was accompanied by steatosis, increased Bax/Bcl-2 ratio, and overexpression of p-SAPK/JNK, Tgfβ1, Map3k14, and Col1a1 in the liver." (PMID 34663892, 2022). "In steatosis hepatocytes sustaining hypoxia/reoxygenation injury, Bax expression was significantly increased and the expression of Bcl-2 was decreased dramatically." (PMID 30232347, 2018). "Bcl-2 seems to play a minor role in the process of steatosis." (PMID 32143527, 2020). "However, the expression of antagonistic protein Bcl-2 is slightly decreased when steatosis is intensified." (PMID 32143527, 2020). "AC extract significantly improved the FFAs-induced steatosis without cytotoxicity and Caspase-3, −9, Bax and Bcl-2 were modulated profitably to HepG2 cells after AC treatment." (PMID 25038800, 2014).
subarachnoid hemorrhage (9 papers, 2017 to 2025). A serious neurological disorder characterized by intracranial hemorrhage into the subarachnoid space. "In particular, this type of polyphenol increased the levels of the anti-apoptotic protein Bcl-2 and tight junction proteins such us Zona Occludens 1 (ZO-1), claudin-5, and occludin, after subarachnoid hemorrhage." (PMID 39796474, 2024). "In a previous study, administration of hydrogen-rich saline showed improved neurological function and decreased neuronal apoptosis in rabbits by upregulation of Bcl-2 and downregulation of the Bax protein in subarachnoid hemorrhage." (PMID 34948107, 2021). "For example in adults, neuroglobin gene haplotype has a strong influence on outcome after TBI, bcl-2 gene single nucleotide polymorphisms also influence outcome after TBI, and apoE genotype predicts outcome following subarachnoid hemorrhage." (PMID 31275228, 2019).
thymoma (9 papers, 2007 to 2024). A neoplasm arising from the epithelial cells of the thymus. "In contrast, A histotype thymomas can exhibit varying levels of BCL2 positivity, ranging from 60 to 100% in different reports." (PMID 38201593, 2023). "Four markers, namely Bax, p73, Casp-9 and Bcl-2, from two articles that included 176 cases of thymoma and 36 cases of thymic carcinoma were selected." (PMID 32993581, 2020). "We further found a relationship between BPAs and degree of malignancy for four markers, namely Bax, p73, Casp-9 and Bcl-2, included 176 thymoma patients and 36 thymic carcinoma patients, and BPAs were significantly correlated with thymic carcinoma (P = 0.010)." (PMID 32993581, 2020). "Previous reports suggested that bcl-2 acts as an inhibitor of apoptosis in thymomas and correlates with aggressiveness in thymic epithelial neoplasms." (PMID 17498299, 2007). "The expression of BCL2 in thymic carcinomas is different from that in thymomas." (PMID 38201593, 2023). "Two of seventeen (11.7%) thymomas (all sporadic B3 type) contained numerous neoplastic epithelial cells positive for CD5 and bcl-2." (PMID 17498299, 2007). "Two of seventeen (11.7%) thymomas (all sporadic B3 type) contained numerous CD5+ and bcl-2+ neoplastic epithelial cells." (PMID 17498299, 2007). "Two of seventeen (11.7%) thymomas (all sporadic type B3) contained numerous CD5+, bcl-2+ neoplastic epithelial cells." (PMID 17498299, 2007). "Another study integrating thymoma tissue and normal thymus transcriptome data identified key transcription factors and signaling pathways such as BCL2 and CXCL13, which may be core mechanisms driving the development of MG thymomas." (PMID 39845831, 2024). "Epithelial cells in thymic carcinomas uniformly express BCL2, while B thymomas typically do not express BCL2." (PMID 38201593, 2023).